RPP38-DT (RPP38 divergent transcript)
Synonyms: C10orf111; MGC35468; bA455B2.4
Gene: Long non-coding RNA gene on chromosome 10 (15,095,385 to 15,097,319, reverse strand). Ensembl gene ENSG00000176236.
Subcellular location: Membrane